DLGAP3 (DLG associated protein 3)
Description:
May play a role in the molecular organization of synapses and neuronal cell signaling. Could be an adapter protein linking ion channel to the subsynaptic cytoskeleton. May induce enrichment of PSD-95/SAP90 at the plasma membrane.
Synonyms: SAPAP3; DAP3; SPAPA3
Tractability: Antibody: its Gene Ontology location is reachable by antibodies, with high confidence; UniProt places it where antibodies can reach, with medium confidence; the Human Protein Atlas places it where antibodies can reach. PROTAC: its protein half-life has been measured.
Gene: Protein-coding gene on chromosome 1 (34,865,436 to 34,929,650, reverse strand). Ensembl gene ENSG00000116544.
Subcellular location: Cell membrane; Postsynaptic density; Synapse
Subcellular location (Human Protein Atlas): Endoplasmic reticulum; Plasma membrane; Midbody
Pathways (Reactome):
Neuronal System: Neurexins and neuroligins
Gene Ontology:
Molecular function: protein binding; molecular adaptor activity; amyloid-beta binding
Biological process: modulation of chemical synaptic transmission; modification of postsynaptic structure; signaling
Cellular component: glutamatergic synapse; plasma membrane; postsynaptic specialization; cholinergic synapse; neuromuscular junction; postsynaptic density; synapse
Genetic constraint (gnomAD): Loss-of-function variants: 17 observed, 69.44 expected, observed/expected ratio (o/e) 0.24, 90% interval 0.17 to 0.37. The upper end of that interval is the gene's LOEUF score, 0.37, which puts it in group 1 of 6, group 1 being the genes least tolerant of losing a copy. Missense variants: 1,124 observed, 1,255.9 expected, observed/expected ratio (o/e) 0.89, 90% interval 0.85 to 0.94. Synonymous variants: 577 observed, 531.18 expected, observed/expected ratio (o/e) 1.09, 90% interval 1.01 to 1.16.
Homologues: Orthologues: chimpanzee DLGAP3 (99% identical), macaque DLGAP3 (99% identical), pig DLGAP3 (98% identical), dog DLGAP3 (97% identical), guinea pig DLGAP3 (97% identical), rat Dlgap3 (96% identical), mouse Dlgap3 (96% identical), rabbit DLGAP3 (86% identical), tropical clawed frog dlgap3 (61% identical), zebrafish dlgap3 (52% identical). Paralogues in human: DLGAP2 (48% identical), DLGAP1 (41% identical), DLGAP4 (37% identical), DLGAP5 (14% identical).
Diseases named in the same sentence as DLGAP3 in open-access papers:
DLGAP3 is named in the same sentence as 21 diseases in open-access papers, as found by Europe PMC text mining. Sharing a sentence is not in itself a finding about the gene and the disease. The quoted sentences say what the papers report.
Anxiety (20 papers, 2016 to 2025). Intense feelings of nervousness, tension, or panic often arise in response to interpersonal stresses. "Lastly, anxiety levels appear to be diminished in SAPAP4-deficient mice, whereas they are increased in Dlgap3−/− animals." (PMID 30664629, 2019). "Knock-out mice for DLGAP3, a scaffolding protein involved in vesicle trafficking in glutamatergic neurons, displayed OCD-like behavior consisting of compulsive grooming and anxiety-like phenotypes." (PMID 27093171, 2016).
trichotillomania (10 papers, 2014 to 2025). A disorder characterized by repetitive pulling out of one's hair resulting in noticeable hair loss; the individual experiences a rising subjective sense of tension before pulling out the hair and a sense of gratification or relief when pulling out the hair. "In patients with OCD and trichotillomania, multiple and rare missense mutations were found in the DLGAP3 gene." (PMID 28870203, 2017). "An association was found between variations in the DLGAP3 gene and trichotillomania, which appeared to be familial." (PMID 28870203, 2017). "Since Dlgap3−/− mice showed OCD-like symptoms, patients with the grooming disorder, trichotillomania (hair-pulling disorder) and OCD were genotyped for SNVs in the DLGAP3 locus." (PMID 28870203, 2017). "The data convincingly depicts the DLGAP3 gene as a disease gene for both OCD and trichotillomania." (PMID 28870203, 2017). "Resequencing of exons of DLGAP3 (the human SAPAP3 gene) revealed excessive rare non-synonymous variants in human OCD and trichotillomania individuals." (PMID 24995881, 2014).
schizophrenia (7 papers, 2014 to 2023). A major psychotic disorder characterized by abnormalities in the perception or expression of reality. "In this study, we identified three additional schizophrenia-associated DLGAP3 missense mutants (DLGAP3H22N, DLGAP3G352E, DLGAP3S455R) in an independent sample of patients with schizophrenia." (PMID 33343614, 2020). "Yet, genetic changes in DLGAP2 and DLGAP3 are considered as susceptibility factors for schizophrenia." (PMID 28870203, 2017). "The DLGAP3/SLC1A1 interaction might be involved in the susceptibility to develop OCS in antipsychotic-treated schizophrenia patients." (PMID 37627285, 2023). "DLGAP2 and DLGAP3 have only been linked to schizophrenia in genetic screens." (PMID 28870203, 2017). "Multiple single nucleotide variations (SNVs) have been reported in DLGAP2 and DLGAP3 genes in schizophrenia patient cohorts." (PMID 28870203, 2017). "Specific genetic risk factors seem to dispose patients with schizophrenia to develop OCS and risk-conferring polymorphisms has been defined in SLC1A1, BDNF, DLGAP3, and GRIN2B and in interactions between these individual genes." (PMID 26556409, 2014). "In summary, specific genetic risk factors predispose patients with schizophrenia to develop OCS induced by antipsychotic treatment, and risk-conferring polymorphisms in genes linked to the glutamatergic system, such as SLC1A1, DLGAP3, and GRIN2B, have been identified." (PMID 37627285, 2023). "We previously detected three rare schizophrenia-associated missense mutations (DLGAP3G381S, DLGAP3G587R, and DLGAP3R770L) in patients with schizophrenia and speculated that they might affect the posttranslational modification of DLGAP3 protein via kinases phosphorylation." (PMID 33343614, 2020). "So far, independent replication approaches regarding BDNF, DLGAP3, and GRIN2B have not been conducted and further studies are needed to untangle the interplay of pharmacological and genetic risk factors for OCS in schizophrenia." (PMID 26556409, 2014). "No functional studies have yet been conducted on DLGAP2 and DLGAP3 in relation to schizophrenia." (PMID 28870203, 2017).
Tourette syndrome (2 papers, 2014 to 2023). A neurologic disorder caused by defective metabolism of the neurotransmitters in the brain. "Recently, Crane J. and collaborators, using linkage analysis study, suggested DLGAP3 as a candidate gene for Tourette syndrome." (PMID 25016475, 2014).
Lymphatic Metastasis (1 paper, 2025). Transfer of a neoplasm from its primary site to lymph nodes or to distant parts of the body by way of the lymphatic system. "Only 6 genes, namely CHGA, CHGB, PCSK2, PCSK1N, DLGAP1 and DLGAP3 were down-Regulated in the lymphatic metastasis group." (PMID 41431044, 2025).
tumor (1 paper, 2025). "High genomic alterations in zesto lesions were inversely correlated with putative tumor suppressor genes (MTUS2, DLGAP3, RTN1, CRLF1, SLC12A5, and PDIA2) and positively correlated with APOBEC mutagenesis (APOBEC3C, APOBEC3G, APOBEC3B, and APOBEC3F) and hypoxia-related gene signatures." (PMID 40319462, 2025).
DLGAP3 also shares sentences with these, for which no sentence is quoted: obsessive-compulsive disorder (12 papers); Alzheimer disease (3); autism (3); Angelman syndrome (1); autism spectrum disorder (1); bipolar disorder (1); brain disorder (1); depression (1); epilepsy (1); fragile X syndrome (1); hearing loss (1); infection (1); Obesity (1); temporal lobe epilepsy (1); tonic clonic seizures (1).